MIRLET7E (microRNA let-7e)
Synonyms: hsa-let-7e; LET7E; MIRNLET7E; let-7e
Gene: MicroRNA gene on chromosome 19 (51,692,786 to 51,692,864, forward strand). Ensembl gene ENSG00000198972.
Gene Ontology:
Biological process: miRNA-mediated post-transcriptional gene silencing
Cellular component: RISC complex
Homologues: Orthologues: chimpanzee ptr-let-7e (100% identical), macaque MIRLET7E (100% identical), guinea pig MIRLET7E (99% identical), pig ssc-let-7e (99% identical), mouse Mirlet7e (97% identical). Paralogues in human: MIRLET7C (73% identical), MIRLET7A2 (72% identical), MIRLET7D (70% identical), MIRLET7F2 (67% identical), MIRLET7A1 (65% identical), MIRLET7F1 (65% identical), MIR98 (62% identical), MIRLET7A3 (62% identical), MIRLET7G (58% identical), MIRLET7I (56% identical).